MMP2 (matrix metallopeptidase 2)
Diseases named in the same sentence as MMP2 in open-access papers (continued):
Sharing a sentence is not in itself a finding about the gene and the disease.
cancer (continued). "Although the present work has some limitations as the zebrafish model is limited in terms of its similarity to mammal models, our results, paired with our previous findings on deflamin, bring a novel view on the use of MMP-2 and -9 inhibitors in cancer models." (PMID 36551666, 2022). "DR6 binding to TRAF4 enhances cancer cell mobility by enhancing MMP2 and MMP9 expression and participating in the PI3K/AKT pathway." (PMID 35242717, 2022). "This leads to the adhesion of CD11b+ myeloid cells and, subsequently, to the generation of MMP-2, which cleaves collagen, enabling recruitment of BMDCs and cancer cells to the TME in the lungs." (PMID 35203510, 2022). "The overexpression of MMP2 in cancer causes the decomposition of ECM and, hence, accelerated cancer invasion and worse prognosis." (PMID 36013494, 2022). "In this regard, MMP2 is well-known to be upregulated in a variety of cancers, suggesting a possible post-translational control of altered LOX enzyme activity or specificity in a cancerous microenvironment." (PMID 35563478, 2022). "Lnc-MMP-2 is exported through cancer cells exosomes into BBB cells and acts as a sponge for the protective miR-1207-5p." (PMID 35884446, 2022). "Cisplatin properties involve a reduction in the migration and invasiveness of cancer cells, which has been shown to be related to decreased MMP2 activity." (PMID 36553576, 2022). "The exosome-activated mCAFs upregulate the activity of genes for MMP-1, MMP-2, MMP-7, MMP-8, MMP-13 and MMP-14 that are associated with cancer growth and progression." (PMID 34837514, 2022). "The EtOH extract, EtOAc soluble fraction, and gallic acid (GA) extractives impaired the motility and invasion of cancer cells by prohibiting migration and proliferation by the downregulation of MMP2, MMP9, Bax, cleaved caspase-3, and Bcl-2." (PMID 36362345, 2022). "Treatment with Iso at both concentrations results in a decrease in proteolytic activity, demonstrated by accumulation of MMP9 proteases in cancer cells, and also by decreased proteolytic fractions of 72 kDa (proMMP2) and active MMP2 (66 kDa)." (PMID 36500428, 2022). "Among the “oncogenic” MMPs, MMP-2 and MMP-9 have been implicated as the most important prognostic factor in cancer microenvironment." (PMID 36544756, 2022). "Circ_MMP2 is involved in an increase of the metastatic potential of exosome-receiving cancer cells via modulating the miR-136-5p/matrix metallopeptidase 2 (MMP2) axis." (PMID 35055115, 2022). "Matrix metalloproteinase-2 (MMP-2) is a main contributor to cancer cell migration, which can be stimulated by PAFR." (PMID 35603177, 2022). "MMPs are vital biomarkers for tumorigenesis, metastasis, and angiogenesis of cancers, and MMP-2 is one of the most important MMPs as it is overexpressed in most solid tumors." (PMID 36451698, 2022). "Whereas MMP-9 is highly upregulated in most types of cancer, MMP-2 expression only modestly increases." (PMID 36539774, 2022). "This will help better design more specific inhibitors targeting subcellular MT1-MMP/MMP-2 to improve the efficacy of therapeutic interventions in cancer and other diseases." (PMID 36076910, 2022). "Knowing that MMP-2 is overexpressed by cancer cells and PS-induced phagocytosis of apoptotic cells, MMP-2-sensitive nanoparticles covered with PS loaded with dasatinib were developed recently by Liu." (PMID 35183252, 2022). "But our study shows that WSP is dose-dependent, and the dose in mice can reach 60μg/g, and the expression of proteins related to cancer metastasis, such as MMP2 and MMP9, is observed to decrease." (PMID 36568183, 2022). "In vitro, PPP-LIP and PP-LIP dramatically increased the cellular absorption of HCPT in SMMC-7721 cells with strong MMP2 expression, resulting in cancer cell death." (PMID 36104946, 2022). "CircPUM1, indeed able to upregulate MMP2 by sponging of miRNA-6753-5p and miR-615-5p, is expressed by cancer cells and transferred to peritoneum." (PMID 35626752, 2022).
cancer (continued). "MMP-2 can degrade collagen indirectly, which can be used to study the migration of cancer cells after labeling." (PMID 35236250, 2022). "MMP-2 and -9 expression levels were reduced in miR-142 overexpressed cancer cells to inhibit migration and invasion of these cells." (PMID 36180575, 2022). "Among the effects of these transcription factors, increased expression of proteases (e.g., MMP-2 and MMP-9) are what cause cancer cells to undergo EMT for promoting cellular detachment and invasiveness." (PMID 35586209, 2022). "According to studies, IBSP can form a trimolecular complex with integrins and MMP2, speeding up local matrix breakdown and cancer cell invasion." (PMID 35741689, 2022). "MMP2 plays a very important role in the occurrence and development of malignant tumors because of its degradable ECM components." (PMID 36147444, 2022). "KLF2 was stably expressed in HCCLM3 cells and thus reduced TGF-β-induced wound healing and cancer cell mobility by intervening TGF-β-stimulated promotion of MMP2." (PMID 35992798, 2022). "MMP2 is elevated in many tumors, and its increase promotes the growth and migration of malignant cancer cells." (PMID 35413833, 2022). "L1CAM is highly expressed in PDAC cells, the expression levels of which are correlated with cancer progression, metastasis, and neural invasion via the induction of metalloproteinase-2 (MMP-2) and MMP-9 in cancer cells." (PMID 36077804, 2022). "Elevated expression of MMP-2 and MMP-9 is indeed considered a hallmark of cancer aggressiveness, and it is suggested that their levels can be useful prognostic biomarkers." (PMID 35008401, 2022). "Baicalein inhibits the expression of MMP-2 and the invasion ability of cancer cells, probably via the p38 MAPK-dependent NF-κB signaling pathway." (PMID 36432119, 2022). "On the other hand, MMP2 is highly expressed and released in various types of cancers, such as colorectal cancer, lung cancer and prostate cancer, and is positively correlated with their progression." (PMID 35927755, 2022). "The matrix metallopeptidase 2 (MMP2) that is known to break down the basement membrane was shown to promote cancer invasion." (PMID 35042889, 2022). "Matrix metalloproteinase(MMP)-2 and -9 are two related zinc-dependent endopeptidases that are critical in cancer cell invasion and migration, and MMP-2 and -9 are expressed at high levels in cancer tissues and invasive cell lines." (PMID 36110092, 2022). "Being one of the main molecular targets of cancer metastasis, attempts to design potential MMP2 inhibitors have been made in the last few decades." (PMID 36077415, 2022). "Hypoxia-inducible factor-1α was reported to transactivate the VEGF and matrix metalloproteinase-2 (MMP-2), both of which are usually upregulated in a variety of cancers and are key regulator in angiogenesis." (PMID 35800233, 2022). "Due to their ability to degrade the essential elements of basement membranes, MMP2 and MMP9, also known as gelatinase A and gelatinase B, are thought to be the significant MMPs involved in the invasion and metastasis of several cancers." (PMID 36430837, 2022). "The activatable peptide consists of anionic (EEEE), cleavable, and cationic sequences (RRRR) that enable intracellular delivery by matrix metalloproteinase-2 (MMP2), which is secreted by living cancer cells." (PMID 35163529, 2022). "During the last years we developed new peptidomimetics as integrin ligands, and successively we moved our attention to the inhibition of MMP2/9 within the context of cancer angiogenesis and metastasis." (PMID 35209039, 2022). "MMP-2 subsequently enhances the migration of cancer cells by degrading the extracellular matrix while also promoting metastasis through the induction of angiogenesis." (PMID 35311154, 2022). "The experimental results showed that MMP2 mRNA expression levels were positively correlated with ATF1 in cancer cells except BGC823 cells (R2 = 0.975, P = 0.002)." (PMID 35397606, 2022).
cancer (continued). "MMP2 is the main proteolytic enzyme among MMPs, and is a main promoter of cancer-cell invasion and metastasis by degrading the basement membrane and accelerating distant metastasis." (PMID 36497431, 2022). "For example, upon upregulating heat shock protein 90α (HSP90α) trafficking, Rab27b-regulated vesicles are required for matrix metalloproteinase 2 (MMP2) activation to facilitate cancer cell motility." (PMID 35927755, 2022). "MMP-2 and MMP-9 proteins are associated with the invasion, proliferation, and metastasis of cancer cells." (PMID 36291760, 2022). "Another metalloprotease MMP2 is upregulated by miR-194, which supports the colonization of distant organs by circulating cancer cells." (PMID 35884446, 2022). "This response of TIMP-1 immediately translocating to the nucleus implies an important role of MMP-2 within the nucleus, requiring regulation, especially within cancer cells." (PMID 36076910, 2022). "On the other hand, the upregulated genes, such as GNG12, GNG4, WNT9A, EDNRB, FGF18, LAMA3, MMP2, etc., were found in pathways in cancer." (PMID 36239109, 2022). "Since both HDACs and MMPs are metalloenzymes that play a role in cancer migration, invasion, angiogenesis, and metastasis, dual MMP2/HDAC8is were designed to enhance the anti-migratory, and anti-invasive properties of selective MMP or HDAC inhibitors." (PMID 36077415, 2022). "Understanding how targeting nuclear MT1-MMP or MMP-2 affects cell proliferation and migration will open new avenues in cancer therapy." (PMID 36076910, 2022). "Exosomal circUHRF1, exosomal circPTGR1, exosomal circRNA-100,338, and exosomal circ_MMP2 occupy a linchpin position in mediating HCC cells communication as well as assisting cancer metastasis." (PMID 36476239, 2022). "Several aptamer-based probes have been developed using upregulated membrane-bound or membrane-associated proteolytic enzymes, such as MMP-2, MMp-7, and MMP-9, for cancer diagnosis." (PMID 36431072, 2022). "MMP-2 was upregulated in AC compared to both other cancer types and adjacent tissue, making it a promising target for future studies." (PMID 35681609, 2022). "Our findings, although inpancreatic cancer, demonstrated that MMP2 expression was the highest of all studyproteins in all collections, being the highest expression found in the secondcollection, in 80% of patients." (PMID 35107490, 2022). "Of note is that MIF has emerged as an inducer of cancer cell migration and invasion by up-regulating and activating matrix metalloproteases (MMPs), such as MMP2, MMP9 and MMP13, then contributed to degradation of ECM." (PMID 36703790, 2022). "The positive staining of Hsp70, MMP14, MMP2, and cortactin was mostly observed in the cytoplasmic of the carcinoma cells, whereas the nucleic positive signals were detected much more in the Hif1α immunohistochemical staining." (PMID 35957827, 2022). "It is documented that induction of MAPK/ERK or PI3K/Akt contributes to cancer cell invasion by regulating MMP-2 and/or MMP-9 40-42." (PMID 34149918, 2021). "Rh2 also diminished metastatic activities of pancreatic (Bxpc-3 at a dose of 45 μM) and lung (A549 at a dose of 60 and 100 μM) cancer cells via inhibition of MMP-2 and MMP-9." (PMID 33671187, 2021). "Myr acts as an anti-cancer agent through different mechanisms including the modulation of MMP-2 and MMP-9." (PMID 33498927, 2021). "Invasive cancer cells have a high level of MMP-2/9 expression, and the expression level of MMP-2/9 in drug-resistant cancer cells is higher than that of drug-sensitive cancer cells." (PMID 33768509, 2021). "This active form cleaves and activates MMP2, one of the gelatinases that have been consistently involved in cancer metastasis." (PMID 33853673, 2021). "We revealed that miR-491-5p also directly targeted RABIF and downregulated RABIF-mediated TNBC cancer stemness, drug resistance, cell invasion, and pulmonary metastasis via matrix metalloproteinase (MMP)-2 and MMP-9 signaling." (PMID 34685504, 2021).
cancer (continued). "Overexpression or highly activation of MMP-2 and -9 to promote cancer cell metastasis has been observed in many cancer cells, such as breast, brain, prostate cancer and HCC." (PMID 33805784, 2021). "In summary, our results demonstrated that MMP-2 plays a major role in cancer progression for its ability to degrade ECM components, and that its expression and activity are up-regulated through IL-6 in T88 and T93 cells." (PMID 34885656, 2021). "IBSP can form a three‐molecule complex with avb3 integrin as well as matrix metalloproteinase 2 (MMP2), and the complex accelerates local matrix decomposition along with cancer cell invasion." (PMID 33987980, 2021). "In this context, elevated expression of SLC12A7 promotes cancer invasion and metastasis through modulation of MMP-2 activity and cell volume control." (PMID 33461589, 2021). "EMT is also associated with the increased expression and activities of MMP-2 and MMP-9, which can stimulate the metastasis of cancer cells." (PMID 33912463, 2021). "These cytokines have been identified to be directly or indirectly responsible for cancer progression through remodeling of ECM by upregulating the expression of molecules such as MMP2, MMP3, MMP9, MMP10, MMP13, PLAU, ICAM1 and VCAM1." (PMID 34946170, 2021). "Metalloproteinases like MMP-2/MMP-9 have been reported earlier to be regulated by FRA-1 in several cancers including GBM." (PMID 34211498, 2021). "Our results showed that, the mRNA and protein of MMP-2 were expressed in both cancer and pericarcinoma tissues, the expression intensity in the cancer tissue being significantly higher than that in the pericarcinoma tissue." (PMID 31882379, 2021). "We observed a significant upregulation of MMP2 transcripts when MSCHigh and THP1s were added to the cancer cells compared to the cancer cells cultured alone." (PMID 34885111, 2021). "There are many reports about α3β1 integrin involvement in MMP-2 activation and cancer cell migration in different types of cancer." (PMID 34199232, 2021). "In contrast to SIRT7, the ectopic expression of nuclear HDAC6 in NSCLC cells inhibits cancer invasiveness by the deacetylation of p65, which, in turn, decreases its binding to the matrix metalloproteinase-2 (MMP2) promoter and reduces MMP2 expression." (PMID 34769241, 2021). "MT1-MMP, an activator of pro-MMP-2 and a potent interstitial collagenase, is also thought to influence cancer cell angiogenesis by promoting the formation of capillary tubes." (PMID 33810259, 2021). "All these nanoplatforms employ gatekeeper systems containing matrix metalloproteinase (MMP)-2 and -9 protease linkers, based on the observation that these MMPs are frequently upregulated in cancer and the fact that MMP cleavages site are well described." (PMID 34282781, 2021). "MMP2/9/13 had been found to play vital functions in the invasion and metastasis of malignant tumors." (PMID 34820358, 2021). "Various cancers that are used as receptors are hCA IX, MMP-2, and RSK2, which have general mechanisms of action in the body." (PMID 34452553, 2021). "In BC, the mechanisms regulating MMP2 expression, and, in turn, promote cancer invasion, have hardly been explored." (PMID 34142438, 2021). "Further, we revealed that preventing crosstalk between CAFs and cancer cells partially inhibits cancer stemness and gemcitabine resistance and decreases the expression of metastasis-related genes such as MMP2, MMP9, and Snail." (PMID 33782384, 2021). "Overall, CHI3L1-induced MMP2 overexpression plays a crucial role in ECM regulation promoting cancer cell growth, proliferation, invasion, and metastasis." (PMID 33846436, 2021). "For instance, fucoidan treatment at a nontoxic dose (0–200 mg/ml) exhibited a concentration-dependent inhibitory effect on the invasion and migration of cancer cells by suppressing MMP2 activity." (PMID 34812264, 2021).
cancer (continued). "The overexpression of specific MMPs including MMP2, 3, 9, 13, 14 has been associated with the induction of EMT program and the acquisition of mesenchymal phenotype and increased aggressiveness of cancer cells." (PMID 33809973, 2021). "Accumulating reports show that overexpression of certain MMPs (e.g. MMP2, MMP3 and MMP9) is associated with EMT during cancer initiation and progression." (PMID 33931048, 2021). "WWOX and AP-2α demonstrated similar anti-cancer functionality in most biological processes with subtle differences in MMP-2/9 regulation; this contradicted that of AP-2γ, whose actions potentiated cancer progression." (PMID 34204827, 2021). "By gelatin zymography, we have shown that MB49 cancer cells secreted pro-forms of MMP-2 and MMP-9 in the culture medium when cultured in vitro." (PMID 34199232, 2021). "Matrix metalloproteinases, which belong to a large family of proteases, have been demonstrated to play vital roles in tissue remodeling and cancer progression and metastasis, of which MMP2 and MMP9 are the most important." (PMID 33573671, 2021). "Many studies have used MMP9 and MMP2 as indicators for evaluating cancer cell invasion and migration ability." (PMID 33732651, 2021). "Elevated levels of miR-145-5p resulted in decreased epithelial ovarian and cancer cell migration through MMP2 and MMP9 downregulation." (PMID 33809973, 2021). "In this study, we used murine models of cancer to dissect the effects of MMP2 in the regulation of immune responses in the TME." (PMID 34032639, 2021). "The higher cancer incidence in female versus male mice contrasts with data from OPSCC patients and is associated with enhanced ER expression via MMP2 upregulation." (PMID 34684173, 2021). "Fibronectin coding genes were found to be up-regulated in studies describing cancer cell migration and various EMT markers such as vimentin, E-cadherin, MMP2 and MMP9, which were all associated with and used to measure cellular invasion." (PMID 33809554, 2021). "Enhanced invasiveness occurs when HSP90α is secreted via exosomes from invasive cancer cells and activates matrix metalloproteinase-2 (MMP-2)." (PMID 34638658, 2021). "The spatial expression of MMP2 in cancer tissue and normal tissue was successfully detected, which having a marked difference." (PMID 34976953, 2021). "Of the four membrane-type matrix metalloproteinases, MT1-MMP is most frequently overexpressed in cancer, and is frequently detected together with the activated form of MMP2." (PMID 34539732, 2021). "The statistical results showed that the expression of MMP2 was higher in the marginal region than in the central region, which was consistent in all cancer tissues." (PMID 34976953, 2021). "Since MMP inhibitors, MMPi III and MMP2 inhibitor I, restored the reduced expression of NKG2DLs after treatment of TGF-β, it was thought that TGF-β induced the expression of MMP2 which facilitated the shedding of the NKG2DLs in cancer cells." (PMID 34253166, 2021). "VEGF, Ki67, Bax, Bcl-2, MTA1, and MMP2 expression in cancer tissues was consistent with those in cancer cells, as revealed by immunohistochemical staining." (PMID 34900992, 2021). "Alternatively, the impact of altered expression of MMP-2 on the secreted proteins can be studied in a model system such as cancer cell lines." (PMID 34429501, 2021). "It inhibited the secretion of the cancer metastasis-relevant matrix metalloproteinases MMP-2 and MMP-9, and also the growth of Staphylococcus aureus biofilms by ca 87% when applied at concentrations as low as 0.5 μg/mL." (PMID 34677482, 2021). "Increased levels of MMP-2/9 are related to the invasion, metastasis, and poor prognosis of various cancers." (PMID 33869638, 2021). "It was revealed that the potential cancer risk predictors are age, 20S proteasome level in exosomes, MMP9 + and MMP9+/MMP2+/EMMPRIN+ subpopulations of CD9-positive exosomes." (PMID 33773551, 2021).